IL6 (interleukin 6)
Diseases named in the same sentence as IL6 in open-access papers (continued):
Sharing a sentence is not in itself a finding about the gene and the disease.
cancer (continued). "Its inhibitory effect on the IL-6/STAT3 pathway also disappears after SOCS inactivation, resulting in continuous proliferation and invasion of cancer cells." (PMID 34976809, 2021). "Recent research showed that chemokines and cytokines, namely, TNF-α, IL-6, and chemokine (C-C motif) ligand 2 (CCL2), have roles in the formation of the cancer microenvironment and are responsible for the migration of inflammatory cells and cancer cells." (PMID 34631699, 2021). "Many inflammatory factors such as interleukin-1beta (IL1b), interleukin-17a (IL17a) and interleukin-6 (IL6) have been reported to facilitate HCC progression by promoting proliferation, metastasis and cancer stem cells (CSCs) formation." (PMID 33661757, 2021). "Our analysis of the amplified cancer genes also identified probable drivers TLK2 and IL6, whose amplification and/overexpression have been implicated in genomic instability and Jak/Stat activation, respectively." (PMID 34313788, 2021). "The known roles of VEGFA, ACKR3, IL6 and FYN establish them as the major regulators of cancer pathways cluster in the network." (PMID 34439877, 2021). "Secretion of proinflammatory adipokines such as tumour necrosis factor-α (TNF-α) and interleukin-6 (IL-6) by dysfunctional adipose tissue and an increase in inflammatory factors, such as C-reactive protein (CRP), are likely to promote cancer development." (PMID 33492550, 2021). "Elevated plasma IL-6 and YKL-40 at the time of diagnosis have been shown to be prognostic biomarkers of short OS in various types of cancer." (PMID 34200156, 2021). "Numerous cell signaling pathways are involved in the initiation and progression of cancer cachexia, including the TNF-ɑ pathway, TGFβ/p38/MAPK pathway, NFκB pathway, IL-6 pathway, IGF/Akt pathway and FOXO1/FOXO3a pathway, among others." (PMID 34724970, 2021). "On the other hand, the combination therapy can reduce the IL-6 expression by 69% relative to the TZB treatment (TZB+ATV−), showing strong neutralizing effect of ATV on CRCC in the TZB-driven anti-cancer therapy." (PMID 34669701, 2021). "Other cytokines like IL-6, IL-19, IL-20, TGF-α, TNF-α, and IL-23 are also known to promote cancer progression." (PMID 34681026, 2021). "Inflammatory cytokines such as TNF-α, IL-6, TGF-β, and IL-10, have been shown to participate in cancer initiation and progression, depending on the balance of pro- and anti-inflammatory cytokines and their relative abundance." (PMID 33466674, 2021). "Based on the reported immunosuppressive potential of MDSCs in malignant tumors, we analyzed the levels of key immunosuppressive mediators (IDO, ARG1, IL-6, and TGF-β1) in AEG patients." (PMID 33854974, 2021). "Strikingly, those patients bearing a CCA with low IL-6 in fibroblasts and a high LC3 and low p62 pattern in cancer cells (L/H/L) were the ones most benefiting from the adjuvant chemotherapy." (PMID 33925189, 2021). "Several cytokines such as IL-6, IL-10, TGF-β, TNF-α, and Nodal can regulate the chemoresistance of cancer cells." (PMID 33754002, 2021). "In colorectal cancer condition, elevated levels of neutrophils at the primary tumor were correlated with the enhanced NETs in the liver, which also induced proinflammatory cytokine (IL-8, IL-6 and TNF-α) production in trapped cancer cells." (PMID 34835236, 2021). "Among these, IL-6 and its intracellular mediator STAT3 have clear links to PCa progression, as they do with other cancer types." (PMID 33808059, 2021). "As was reported, several hub collagen-related genes including FN1, IL6, COL4A4 and COL7A1 were involved in the progression and development of variable cancers." (PMID 34960256, 2021). "The main molecular players in the inflammation-to-cancer axis are proinflammatory mediators such as TNF-α and IL-6." (PMID 34447314, 2021). "The EBV lytic protein BRLF1 activates the IL6/JAK/STAT3 pathway and promotes cancer by inducing cell migration in NPC cells." (PMID 35008199, 2021).
cancer (continued). "When the TME is enriched in IL-6, IL-1β and TNF-α, DCs achieve a maturation state that activates the adaptive immune system in order to destroy infected or cancer cells." (PMID 34571894, 2021). "It is also possible that already elevated levels of cytokines such as IL-6 and TNF-α in cancer patients offer protection in the initial stages of SARS-CoV-2 infection, offering a certain degree of immune-preparedness." (PMID 34830872, 2021). "Logistic regression analysis including the eight cytokines increased in cancer compared to control (GMCSF, IL-1β, IL-6, IL-8, Rantes/CCL5, MIP1α, TNFα, MCP1) was performed." (PMID 35048057, 2021). "Ang II promotes tissue inflammation by stimulating the synthesis and secretion of MCP-1 or proinflammatory cytokines, such as interleukin-6 (IL-6) and tumour necrosis factor-α (TNF-α), in endothelial cells, cancer cells and haematopoietic cells." (PMID 34620946, 2021). "For example, ZEB1 controls inflammatory factor IL6, IL8 and IL1β production, which can induce cancer metastasis." (PMID 34916487, 2021). "We selected the eleven cytokines that were significantly increased in cancer (GMCSF, IL-6, IL-1β, Rantes/CCL5, MIP1α, MIP1β, TNFα, MCP1/CCL2, IL-8, IL-12p40, IL10) and selected all the positive Pearson's correlations with r > 0.8 and significance of p < 0.01." (PMID 35048057, 2021). "In general, IL-6 cytokines activate EMP processes, fostering the acquisition of mesenchymal features in cancer cells." (PMID 34361105, 2021). "The induction of aerobic glycolysis by LMP1 leads to increased secretion of IL-1β, IL-6, IL-18, and GM-CSF, which in turn promotes MDSC differentiation and expansion as well as cancer cell proliferation and resistance to apoptosis." (PMID 33718235, 2021). "Niclosamide has been reported to interfere with multiple signaling pathways, including mTORC1, IL-6/JAK/STAT3, ERK, Src, and Wnt signaling in different lineages of cancer cells." (PMID 34272475, 2021). "Adipocyte-secreted interleukin-6 (IL-6) and leptin reportedly induce and regulate epithelial–mesenchymal transition (EMT) in cancer cells." (PMID 34561446, 2021). "In particular, EwS EVs induced the release of IL-6, IL-8, and TNF by myeloid cells, consistent with similar findings in other cancers." (PMID 34440851, 2021). "More importantly, shRNA-mediated stable silencing of IL6 in U251 cells markedly abrogated the ability of TGF-β to promote sphere formation and the expression of core cancer stemness genes at the protein level." (PMID 33576874, 2021). "In this section of the review, we will summarise the functional implications of IL-6 and OSM induction of EMP in cancer cells." (PMID 34361105, 2021). "STAT3 target genes, VEGF, IL-10, and IL-6 are transcriptionally regulated by STAT3 and are propagated from cancer cells to immune cells." (PMID 34639131, 2021). "MSCs release specific molecules such as epidermal growth factors (EGFs), IL-8/IL-6 cytokines and CXCL1/2/12 chemokines which directly act on cancer cells in a paracrine fashion and increase cellular proliferation by induction of phenotypic modification." (PMID 34122412, 2021). "Cancer cells promote neutrophil ET formation and are closely related to the inflammatory cytokines ICAM-1, VCAM-1, E-selectin, IL1, IL6, CXCL1, and C3a receptors." (PMID 34084158, 2021). "Mean concentrations of IL-6 in blood serum in the control group and in patients with FIGO I and II cancer were significantly lower than in patients with FIGO III and IV cancer." (PMID 34572929, 2021). "The present study shows that CK2 down-regulation induces the nuclear import of NF-κB by reducing the IκB levels, which promotes the subsequent expression of SASP factors, such as IL-6, IL-1β, and MMP3 in human cancer cells." (PMID 33401686, 2021). "Overall, the role of IL-6, IL-11 as well as of other interleukins, has been observed in MDR cancer cells; the clinical attempts to block their effects for therapeutic intervention have been described in a recent review." (PMID 34503172, 2021).
cancer (continued). "Such an alteration causes physical changes in the extracellular microenvironment, inducing the secretion of cytokines such as interleukin-6 (IL-6) and tumor growth factor-β (TGF-β) from cancer cells to enhance cancer malignancy." (PMID 34957091, 2021). "More specifically, IL6 secretion by acid-reprogrammed MSCs further expands the CSC subpopulation of OS, and induces cancer cell migration." (PMID 34071200, 2021). "Further linking proinflammatory functions of NF-κB, O-GlcNAcylation and cancer, Ser-395 O-GlcNAcylation of TAB1 is required for NF-κB activation and expression of IL-6 and TNF-α." (PMID 34722537, 2021). "Overall, most of the findings reported in this section point to similar molecular and functional consequences of IL-6 and OSM-induced EMP in cancer cells." (PMID 34361105, 2021). "CAF produce numerous factors acting on cancer cells to promote glycolytic metabolism, proliferation, invasion, angiogenesis and metastatic colonisation, including CCL5, CXCL10, IL‐6, TGFα, SDF and versican." (PMID 34841720, 2021). "More recently, TME cytokines, such as IL-6 and HGF, were demonstrated to have clinical relevance and induce cancer cell stemness concomitantly enhancing the epithelial-to-mesenchymal transition (EMT), cell migration, and metastatic potential." (PMID 34408135, 2021). "Thanks to IL-6 autocrine and paracrine stimulus, CAFs upregulate VEGF, activate the JAK2/STAT3 pathway, express MCP-1, CCL11/8/20, CXCL5 and IL-9 for cancer cell invasion, growth and survival." (PMID 34944856, 2021). "IntracellularIL-1R2 regulates IL-6 and VEGF-A expression and the migration and proliferation ofcolorectal cancer cells." (PMID 33704402, 2021). "Another important component of the TME are cancer stromal fibroblasts (CAFs), which in CRC, also produce IL-6, further enhancing the interaction with the TME." (PMID 34299049, 2021). "STAT3 can cooperate with other signalling nodules (mainly Src, SMAD and c-Myc) to mediate IL-6 and OSM promotion of EMP in cancer cells." (PMID 34361105, 2021). "Recently, it was shown that IL-6 secreted by human and murine PSCs stimulated STAT3-dependent cancer cell survival, migration, and metastasis." (PMID 34440697, 2021). "This was followed by development of the gold standard cytokine cocktail comprising IL‐1β, IL‐6, TNFα, and PGE2, as maturation signals for DCs;93, 94 however, MoDCs derived using this cocktail proved ineffective for cancer immunotherapy." (PMID 32663904, 2021). "In summary, there is strong experimental evidence supporting the role of the transcription factor STAT3 as the main mediator of EMP induction by IL-6 and OSM in cancer." (PMID 34361105, 2021). "It has been reported that inflammatory cytokines such as interleukin-6 (IL-6) and tumor necrosis factor alpha (TNF-α) in the TME are able to enhance PD-L1 expression in cancer cells, contributing to escape from T cell immune surveillance." (PMID 33514004, 2021). "Among the results, the expression levels of CD34, IL6, SPI1, and SELL showed significant expression differences in 16, 12, 12, and 11 cancer types, respectively, especially in BRCA." (PMID 33869191, 2021). "In patients who developed cancer recurrence and had low SMA on staging CT TAP, significantly higher systemic levels of CRP, IL-6, VEGF, and expression of cell surface receptor CD14 were observed." (PMID 34459908, 2021). "Interleukin-6 (IL-6), a proinflammatory cytokine, is a representative factor of SASP, and is known to promote the proliferation of cancer cells." (PMID 34948029, 2021). "Except for genes that had been shown to be mis-regulated in many cancer types, such as CDKN2A, CCND1, and IL6, we also detected a cohort of genes that had been newly or rarely reported in LC." (PMID 33628593, 2021). "Cytokines, such as IL-6, IL-17 and IL-23 produced by the NF-κB or STAT3 signaling pathway, induce cancer proliferation and metastasis by promoting TAMs to inhibit a cytotoxic T cell response." (PMID 34683963, 2021).
cancer (continued). "For example, it has been shown that the secretion of pro-inflammatory factors including MMP-9, IL-6 and TGF-β1 from monocytes was upregulated in response to cancer-derived EV stimulation." (PMID 33984826, 2021). "IL-6 was previously reported to induce the expressions of COX-2 34, 35, MMP-9 36, Oct3/4 37, SOD2 38, 39 and CAT 39 in cancer cells." (PMID 33854627, 2021). "In hepatocellular carcinoma, CAFs and cancer cells induced the M2 polarization by upregulating the mRNA levels of CD206 and CD163, and downregulating in the macrophages IL-6 mRNA expression and secretion." (PMID 34680425, 2021). "Regardless of the specific metabolic control exerted over cancer cells by inflammatory factors during PC, TNF-α, IL6, TGF-β, and IL10 are shared mediators for the initiation and progression of several cancer types." (PMID 34205944, 2021). "Senescence is associated with the secretion of a vast array of cytokines, chemokines and growth factors, such as CCL2, IL-6, VEGF and TGF-β, which can aid cancer cell survival and, thus, contribute to therapeutic failure." (PMID 34298736, 2021). "TNF-α, IL-6, and TGF-β are inflammatory cytokines that participate in both the initiation and progression of cancer." (PMID 33567693, 2021). "CH13L1 promotes inflammatory cytokine production (including TNF-α, IL-1β, IL-6, and IFN-γ), connective tissue growth, fibrosis, and cancer proliferation." (PMID 33498689, 2021). "Our in vitro data suggest that the IL-6 and JAK2/STAT3 pathways suppress STING function in cancer cells." (PMID 33790360, 2021). "As we will describe next, both miRNA families have been shown to be modulated by IL-6 and OSM in cancer cells." (PMID 34361105, 2021). "Myeloid-derived suppressor cells (MDSCs) release chemokines including IL-6, VEGF, FGF-2 and MMP-9 to promote cancer progression and bone metastasis." (PMID 34831167, 2021). "IL-6 activates an “M2” specific enzyme, Arginase-1 (ARG1), that can alter the extracellular matrix composition to drive cancer progression." (PMID 34566949, 2021). "Considering the results of these studies together, it is remarkable the relevant role of cytokines, in particular of IL-6, in the activation of STAT3 signaling pathway, which finally allows cancer cells to become more resistant to IR." (PMID 34141616, 2021). "The CXCL1 is often cosecreted with inflammatory cytokines such as IL-1, IL-6, and TNF-α by infiltrating macrophage or cancer cells." (PMID 34803728, 2021). "Senescent human fibroblasts can secrete IL-6 and CXCL8 to promote cancer cell invasion and metastasis." (PMID 35011369, 2021). "Modulators secreted by pCAFs, such as TGF-β, IL-6 and CXCL12, are able to promote the proliferation and invasion of cancer cells." (PMID 34635121, 2021). "CAF-derived IL-6 can induce EMT in multiple cancers, which is usually accompanied with an enhanced migratory capacity of cancer cells and consequential invasion." (PMID 34572947, 2021). "In general, IL-6 and OSM induce EMP in cancer cells by favouring the acquisition of mesenchymal traits and cancer stem cell (CSC)-associated features." (PMID 34361105, 2021). "This protein is mainly produced by hepatocytes, whereas other circulating biomarkers of inflammation, such as IL-6 and YKL-40, are secreted by inflammatory, stromal, and cancer cells." (PMID 35008324, 2021). "Another role of autophagy in maintaining cancer stem cells is by regulating CD24 expression and IL6 secretion." (PMID 33743781, 2021). "A pro-inflammatory cytokine, IL-6, and an oxidative stress response enzyme, cyclooxygenase 2 (COX-2), are involved in inflammatory processes and cancer progression 36, 51-57." (PMID 33854627, 2021). "Initial investigations using this redesigned flow 2 device showed how flow can impact on the metastatic potential of these cancer 3D models, including a novel flow-mediated increase in VEGF and IL-6 cytokine levels present in the effluent media." (PMID 34504636, 2021).
cancer (continued). "Beyond representing markers for Bpep and Dpep activity, IL6, IL8 and ASNS have potential relevance for cancer treatment." (PMID 34065488, 2021). "Pro-inflammatory cytokines, such as interleukin (IL)-6, IL-1β, and tumor necrosis factor-α (TNF-α), promote cancer progression." (PMID 34833849, 2021). "CAF-derived soluble factors including IL6, IL17A, IGF1, IGF2, and nitric oxide indirectly can mediate the development of cancer treatment resistance." (PMID 32932015, 2021). "In particular, IL6, IL10, IL13, VEGF, and TGF-β are secreted by TME inflammatory elements and cancer cells during PC." (PMID 34205944, 2021). "Notably, IL-6 is a key protumoral cytokine, whose production is regulated by the Mincle/Syk/nuclear factor κB (NF-κB) signaling circuit in TAMs,7 suggesting that shMincle effectively inhibits this protumoral axis and may produce anti-cancer effects in vivo." (PMID 34589582, 2021). "Increased levels of inflammatory cytokines, such as IL-6, IL-8, and TNF-α, are known to promote migration, invasion and metastasis of various types of cancer and inhibition of these pathways represent a promising approach in cancer treatment." (PMID 33430013, 2021). "Inflammatory mediators such as TGF-β and IL-6 have been reported to aid the metastasis and invasion of cancer cells 53, TNF-α mediates the transition from chronic inflammation to cancer by acting as a master switch." (PMID 34345201, 2021). "C26 adenocarcinoma led to significant cancer cachexia accompanied by muscle degeneration with disturbed muscle regeneration, high TNF-α and IL-6 levels, MAPK activation leading to increased atrogin-1/MuRF-1 levels, and lipolysis." (PMID 34262449, 2021). "While HBZ appears to specifically target the IL-6-JAK-STAT3 pathway, cancer-related gene products of the PI3K-AKT-mTOR, TGF-β and IL-2-STAT5 pathways are more enriched in the Tax interactome." (PMID 34543356, 2021). "Inflammatory mediators, including TNF-α, IL-6, TGF-β, and IL-10, have been widely incriminated in chronic inflammation and the progression of cancers." (PMID 34165442, 2021). "IL-6/STAT3 mediated miR-200c transformation and inhibited EMT process in breast and lung epithelial cancer cells." (PMID 34722553, 2021). "In this context, IL-6 signaling drives the compartmental translocation of MSH3 and the EMAST cancer phenotype." (PMID 33923292, 2021). "Succinctly, BAs stimulate/decrease the secretion of inflammatory factors such as IL-6 and TNF-α on the one hand, thereby activating/inactivating signal pathways related to cancer promotion to improve/inhibit cancer growth or invasiveness." (PMID 35127481, 2021). "Given the various roles of IL-6 and MCP-1 in promotion of cancer progression and metastasis, an increased secretion of IL-6 and MCP-1 by the vascular endothelium in response to the presence of PNA likely will have a broad and positive impact on metastasis." (PMID 34223877, 2021). "Computational analysis was performed on the Cancer Genome Atlas (TCGA) datasets to explore the role of IL6, IL6R, IL6ST, and IL6R transmembrane isoform expression and their epigenetic regulation in different cancer types." (PMID 34576335, 2021). "The anti-cancer effects of AA phyto-extracts could be attributed to the presence of casticin and chrysosplenol D, which were found in greater amounts in our samples and are able to inhibit the cell migration and pro-inflammatory cytokine production (i.e., IL-1β, IL-6, and MCP-1) induced by LPS." (PMID 34356599, 2021). "For example, the expression levels of IL-6 and the JAK/STAT3 pathway are elevated in degenerative lumber disc tissues, which have often been observed in various cancer tissues." (PMID 34321087, 2021). "We have previously demonstrated that high levels of IL-6, CRP, and other pro-inflammatory cytokines in patients with advanced cancer was correlated with high levels of ROS and low levels of antioxidant enzymes." (PMID 33550983, 2021).